BTN3A1 (butyrophilin subfamily 3 member A1)
Diseases named in the same sentence as BTN3A1 in open-access papers (continued):
Sharing a sentence is not in itself a finding about the gene and the disease.
lupus (1 paper, 2025). "In this study, we found that highly expressed BTN3A1 in SLE patients was significantly associated with severe clinical manifestations, such as lupus nephritis, and correlated with SLEDAI score." (PMID 40959207, 2025). "We demonstrated that BTN3A1 inhibited IL‐38 secretion, and then promoted inflammation and induced lupus‐like alterations." (PMID 40959207, 2025). "Collectively, these findings indicate that the BTN3A1 gene knock‐in exacerbates inflammation and elicits lupus‐like manifestations." (PMID 40959207, 2025). "Indeed, BTN3A1KI mice were able to express the human‐derived BTN3A1 gene, and the mouse model of lupus induced by pristane was able to develop dysregulated immune milieu and systemic organs damage similar to human SLE." (PMID 40959207, 2025). "Finally, we demonstrated that BTN3A1 promotes inflammation and induces lupus‐like diseases by inhibiting the IL‐38‐iron death axis through BTN3A1." (PMID 40959207, 2025). "We further discussed the role of the knock‐in BTN3A1 gene in lupus development." (PMID 40959207, 2025). "Our data revealed amelioration of BTN3A1‐induced lupus‐like changes, such as improved degree of renal injuries and reduced percentage of CD3+, CD8+ T cells, Th1, Th2, Th17 cells, upregulated percentage of Treg cells, and lower expression of IL‐4, IL‐6, IL‐10, IL‐17A, IFN‐γ, TNF‐α, and dsDNA." (PMID 40959207, 2025). "However, our study showed that a 50 μg/kg IL‐38 dose was more effective than 100 μg/kg in reducing BTN3A1‐induced inflammation and lupus‐like phenotype, although both reversed the inflammatory responses and renal damages (higher doses were only significantly effective in some indicators)." (PMID 40959207, 2025). "In summary, this study found that BTN3A1 expression was increased in SLE patients, and BTN3A1 inhibited the IL‐38‐ferroptosis axis, and then, promoted inflammation and induced lupus‐like disease." (PMID 40959207, 2025). "Overall, we confirmed that BTN3A1 inhibition of the IL‐38‐ferroptosis axis affects CD4+ T cell biological activity and is involved in lupus pathogenesis." (PMID 40959207, 2025). "This was confirmed in our in vivo experiments in which BTN3A1 increased the proportion of CD4+ T cells (including a higher percentage of Th1, Th2, Th17 cells and a lower percentage of Treg cells) in the lupus‐like mice." (PMID 40959207, 2025). "In BTN3A1 gene knock‐in (BTN3A1KI) mice, inflammation and lupus‐like manifestations occurred, including increased proportions of Th1, Th2, and Th17 cells, decreased Treg cells, elevated levels of inflammatory cytokines and anti‐dsDNA antibodies, renal injury, and suppressed IL‐38 serum levels." (PMID 40959207, 2025). "Thus, our findings strongly indicated that BTN3A1 is functionally indispensable in promoting CD4+ T cells proliferation and apoptosis in the lupus‐like mice." (PMID 40959207, 2025). "There were higher plasma levels of BTN3A1 in SLE patients with lupus nephritis compared to patients without lupus nephritis." (PMID 40959207, 2025).
Lymph node metastasis (1 paper, 2022). "High BTN3A1 expression was associated with lymph node metastasis and advanced T stage." (PMID 36418890, 2022). "Lymph node metastasis (N stage) (p = 0.001) and tumor invasion (T stage) (p = 0.032) were significantly correlated with high BTN3A1 expression." (PMID 36418890, 2022).
malaria (1 paper, 2018). Malaria is a serious and sometimes fatal disease caused by a parasite that commonly infects a certain type of mosquito which feeds on humans. "A notable exception is the BTN3A1-mediated sensing of PAgs by Vγ9Vδ2 T cells, which underlies their responses to tumors and infections like TB or malaria." (PMID 29755480, 2018).
metastatic clear cell renal carcinoma (1 paper, 2023). "Supportive of the immunomodulatory activity of BTN3A1, the concentration of soluble BTN3A1 found in the plasma of metastatic clear cell renal carcinoma patients was found to predict therapeutic responses to the checkpoint immunotherapeutic nivolumab." (PMID 37240071, 2023).
ovarian tumor (1 paper, 2023). "In 2010, BTN3A1 was found to be widely expressed on immunosuppressive cells found within the ovarian tumor microenvironment and to function as a suppressor of T cell activity by leveraging in vitro studies utilizing K562 cells ‘presenting’ BTN3A1 on their surface." (PMID 37240071, 2023).
prostate tumors (1 paper, 2023). "Here, we show that these stress-associated ligands, in addition to BTN3A1, are expressed by bone metastatic prostate tumors, and their expression in biopsies may help select patients who will respond best to γδ CAR-T cell therapies in prospective clinical trials." (PMID 37134157, 2023). "In our analysis of the SU2C/PCF Dream Team dataset, we found BTN3A1 and BTN2A1 transcripts to be expressed in bone metastatic tumors at similar levels to prostate tumors and soft tissue metastases to the liver and lymph nodes." (PMID 37134157, 2023).
psoriasis vulgaris (1 paper, 2025). Plaque psoriasis is the most common presentation of psoriasis. "Similarly, another study showed that upregulation of BTN3A1 in monocytes leads to activation and accelerated proliferation of Vγ9Vδ2+ T cells in patients with psoriasis vulgaris." (PMID 40959207, 2025).
sarcoidosis (1 paper, 2025). Sarcoidosis is a multisystemic disorder of unknown cause characterized by the formation of immune granulomas in involved organs. "Among 19 protein-sarcoidosis associations, strong genetic colocalization evidence was observed for 8 pairs, including BTN3A3, ANXA11, ITPKA, BTN3A1, G3BP1, IL1RN, IL2RB, and NFKB1." (PMID 40075078, 2025).
testicular germ cell tumor (1 paper, 2021). A germ cell tumor arising from the testis. "However, higher expression of BTN3A1 indicated poor prognosis in patients with testicular germ cell tumors (TGCT)." (PMID 34293829, 2021).
tumor (63 papers, 2012 to 2026). "MYC, TBX21 and BTN3A1 were found to be associated with the immune infiltration in the tumor tissues, especially related to the infiltration of T cells.As is well-known, a high infiltration of immune cells into tumors indicates better patient survival rates." (PMID 41343099, 2025). "MVP dysfunction in tumor cells causes PAg accumulation, resulting in the activation of RhoB and its repositioning from the nucleus to the vicinity of BTN3A1." (PMID 40558272, 2025). "It has been demonstrated that BTN3A1 is significantly associated with T cell function in the tumor microenvironment." (PMID 40959207, 2025). "For example, BTN3A1 is associated with tumor‐infiltrating immune cells and is co‐expressed with a variety of immune checkpoints in patients with breast cancer (BRCA) and non‐small cell lung cancer (NSCLC)." (PMID 40959207, 2025). "(L2)P4 reactivates latent EBV, which increased BTN2A1 and BTN3A1 expression and conferred higher susceptibility towards Vδ2 T cells cytotoxicity in vitro, as well as enhanced tumor regression in vivo by adoptive transfer of Vδ2 T cells." (PMID 36632221, 2023). "The results showed that BTN3A1 expression was negatively associated with tumor purity and positively correlated with infiltration levels of B cells, CD8+ T cells, CD4+ T cells, macrophages, neutrophils, and dendritic cells." (PMID 34293829, 2021). "It is revealed that BTN2A1 and BTN3A1 are co-associated on the surface of tumor cells, and are both required for phosphoantigen recognition by Vγ9Vδ2 T cells." (PMID 32413966, 2020). "The downregulated BTN3A1 may be associated with the decrease of tumor‐infiltrating immune cells such as CD8+ T cells, dendritic cells, γδ T cells, and NK cells, leading to suppression of tumor inhibition effects and worse prognosis of patients." (PMID 34293829, 2021). "Activity depends on tumor BTN3A1 expression and phosphoantigen availability; suppressed in TGF-β-rich TME." (PMID 40558272, 2025). "Investigating the function of BTN3A1 and its expression in tumor tissues has provided new targets for tumor immunotherapy, allowing researchers to explore novel immune therapeutic strategies to enhance the immune response against tumors." (PMID 40558272, 2025). "Recent studies propose using agonistic monoclonal antibodies targeting butyrophilin subfamily 3 member A1 (BTN3A1) to enhance Vδ2 T cell activation and cytotoxicity against tumor cells." (PMID 40148988, 2025). "The group of Zsolt Sebestyen in 2016 found that RhoB modulates the capacity of tumor cells to stimulate Vγ9Vδ2 T cells by coordinating BTN3A1 within the cell membrane." (PMID 40558272, 2025). "Our data establish Vγ9Vδ2 T cell as a potent anti‐CC immune cell that can synergize with αβ T cell through direct tumor‐killing, antigen presentation and relieving BTN3A1‐mediated αβ T cell inhibition." (PMID 40091603, 2025). "For instance, it has been reported a bispecific γδ T cell engager (GADLEN), containing heterodimeric BTN2A1 and BTN3A1 extracellular domains (ECD) fused via inert Fc linkers to scFv domain targeting a tumor-antigen (CD19 or CD20)." (PMID 39144149, 2024). "For example, BTN3A1 inhibits the activation of tumor-killing αβ T cells and γδ T cells by preventing the N-glycosylation process in tumor development." (PMID 38169557, 2024). "Agonistic antibodies targeting BTN3A1 that can mimic the conformational changes that occur upon binding of pAgs have been shown to restore αβ T‐cell anti‐tumour activity while simultaneously inducing γδ T‐cell‐mediated cytotoxicity." (PMID 38375329, 2024). "Elevated expression of BTN3A1 in tumor cells regulated by the mevalonate pathway facilitates the recruitment of BTN2A1 thereby activating the Vγ9Vδ2 T cells." (PMID 39624111, 2024). "The increased P4-induced BTN2A1/BTN3A1 expression possibly triggered higher activation of the infiltrated Vδ2 T cells for cytotoxicity that lead to tumor regression as observed." (PMID 36632221, 2023).
tumor (continued). "For example, the use of an agonistic BTN3A1 antibody, which binds to BTN3A1+ cancer cells, triggers phosphoantigen-like Vγ9Vδ2 T activation and tumor recognition A phase I/IIA clinical trial of this strategy is currently underway (NCT04243499)." (PMID 37989744, 2023). "On the other hand, we reported that BTN3A1 is the main butyrophilin expressed by tumor epithelial cells in CRC." (PMID 36765569, 2023). "Overall, this study demonstrated that Vδ2 T cells can successfully inhibit NPC tumor growth when the hurdle of sufficient BTN2A1/BTN3A1 expression are overcame by use of the EBV-reactivating agent (L2)P4." (PMID 36632221, 2023). "Physiologically, upregulation of the mevalonate pathway in tumor cells results in the accumulation of phosphoantigens, such as isopentenyl pyrophosphate, which induce conformational changes of BTN3A1 in these cells." (PMID 38274800, 2023). "Vδ2 T cells are activated by recognition of phosphoantigens (pAgs) presented by BTN2A1/BTN3A1 on the tumor cells 26-28." (PMID 36632221, 2023). "A first-in-class humanized anti-BTN3A1 antibody was designed to harness and enhance Vδ2 cell–driven anti-tumor activity against multiple tumor cell lines and primary tumor cells, opening promising perspectives." (PMID 37426670, 2023). "Following phosphoantigen binding to the intracellular B30.2 domains of BTN3A1 in tumor cells, BTN3A1 undergoes a conformational change and promotes the interaction between BTN2A1 and BTN3A1 intracellular domains." (PMID 36685942, 2022). "Targeting BTN3A1 with the agonistic antibody CTX-2026 induced BTN3A1 switching from immunosuppressive to immunostimulatory conformations and promoted coordinated Vγ9Vδ2+ and CD8+ αβ T-cell anti-tumor responses against BTN3A1+ tumors." (PMID 35880177, 2022). "BTN3A1 showed a significant immunoregulatory function exerted through modulation of the anti-tumor immune response and activation of γδ T cells." (PMID 36212445, 2022). "We revealed for the first time that BTN3A1 promotes tumor cell radioresistance by activating autophagy." (PMID 36418890, 2022). "At present, it has been confirmed that BTN3A1 can kill tumor cells by activating Vγ9Vδ2 T cells, which indicates that it is related to tumor immunity, but little is known about BTN3A2 and BTN3A3." (PMID 36059652, 2022). "Following phosphoantigen binding to the intracellular B30.2 domains of BTN3A1 in tumor or pathogen-infected cells, BTN3A1 undergoes a conformational change and promotes the interaction between BTN2A1 and BTN3A1 intracellular domains." (PMID 35880177, 2022). "IHC staining revealed that LC3B protein expression was positively correlated with BTN3A1 expression in tumor tissues (r = 0.867, p < 0.001)." (PMID 36418890, 2022). "BTN3A1 promoted xenograft tumor growth, as reflected by an increase in tumor mass and heavier tumor weight." (PMID 36418890, 2022). "Recently, it has been confirmed that the decrease of transmembrane protein BTN3A1 migration on target tumor cells is a key determinant of Vγ9Vδ2 T cell activation." (PMID 34149914, 2021). "Our results showed that BTN3A1 was lower in tumor samples than in counterpart normal controls in 46 (70.8%) of 65 NSCLCs, detected by qPCR, western blot, and IHC." (PMID 34293829, 2021). "Among them, BTN3A1 is widely expressed in immune cells and tumor cells and can regulate the immune response of T cells, especially the γδ T cells." (PMID 34293829, 2021). "BTN3A1 can inhibit tumor responsive αβ T‐cell receptor activation by preventing N‐glycosylated CD45 from dissociation from the immune synapse." (PMID 34293829, 2021). "In BRCAs, BTN3A1 was lower in tumor samples than in counterpart normal controls in 31 (81.6%) of 38 patients' samples, detected by western blot and IHC assays." (PMID 34293829, 2021). "Another step in this process is the small GTPase RhoB, which was recently identified in a genome-wide screen as an important component in BTN3A1-dependent tumor cell recognition by Vδ2Vγ9 T cells." (PMID 28649364, 2017).
tumor (continued). "RhoB interacts with and regulates the membrane mobility of BTN3A1, and intracellular redistribution of RhoB in different tumor cells correlated with their recognition by γδ T cells." (PMID 28649364, 2017). "Furthermore, BTN3A1 was highly expressed in tumor tissues of CC, as revealed by transcriptomics and immunohistochemistry analyses." (PMID 40091603, 2025). "Notably, functional experiments confirmed that BTN3A1 acted as a tumor suppressor in OS, highlighting it as a promising therapeutic target." (PMID 41343099, 2025). "Although the inhibitory effect of BTN3A1 on the activation and killing capacities of αβ T cell has been reported, the regulatory mechanism of BTN3A1 expression in tumor cells remains unclear." (PMID 40091603, 2025). "By using both in vitro and in vivo models, we found that expanded pVγ9Vδ2 T cell is not only a strong tumor killer, but also capable of potentiating the antitumor effect of αβ T cell by antigen presentation and counteracting BTN3A1‐mediated αβ T cell inhibition." (PMID 40091603, 2025). "Besides, BTN3A1 was found as a tumor suppressor in OS, highlighting it as a promising therapeutic target." (PMID 41343099, 2025). "5.9% of cells co-expressed BTN2A1/BTN3A1, suggesting that Vδ2 T cells with full functional capacity could potentially target 32.7% of cells in the tumor if unhindered by the presence of PD-L1 or blocked by αPD-1." (PMID 38077396, 2023). "Therefore, CD277-specific antibodies can restore the effector activity of αβT cells and induce BTN3A activity to mediate the synergistic killing of BTN3A1+ tumor cells by αβT cells and γδT cells in a BTN2A1-dependent manner." (PMID 36793048, 2023). "Considering that the BTN3A1 levels were comparable between BCSC5 culture cells and xenograft-derived tumor cells, we hypothesized that the loss of HMGCR expression was responsible for unresponsiveness of γδ T cells due to low pAg levels in the tumor cells." (PMID 37139603, 2023). "Furthermore, BTN3A1 is detected in CRC at the tumor site, on epithelial and stromal cells, often close to areas infiltrated by Vδ2 T lymphocytes, making conceivable the use of N-BPs in therapeutic schemes against CRC." (PMID 36765569, 2023). "Additionally, the study explores two strategies to re-sensitize tumors in the weak anti-tumor effect (WAT) group: utilizing a BTN3A1 agonistic antibody or employing bisphosphonates to inhibit farnesyl diphosphate synthase (FPPS)." (PMID 37770968, 2023). "We generated a xenograft mouse model using KYSE150 cell lines with stable BTN3A1 knockdown, and the specific tumor area was irradiated to validate whether BTN3A1 knockdown sensitizes ESCC cells to radiation in vivo." (PMID 36418890, 2022). "In addition, targeting of BTN3A1 has been shown to transform BTN3A1 from an immunosuppressive to an immunostimulatory molecule, by inducing γδ T-cell-mediated anti-tumor cytotoxicity, resulting in the killing of specific tumor cells by γδ T cells." (PMID 36212445, 2022). "Vγ9δ2 T cells, a specific γδT cell subset mainly found in the blood, recognize members of the butyrophilin (BTN) family, namely BTN2A1, through the gamma chain of their Vγ9δ2TCR, and additionally require BTN3A1 expression on the tumor cells for full activation." (PMID 36685546, 2022). "In addition, we found that elevated BTN3A1 expression promoted tumor cell growth in vitro and in vivo." (PMID 36418890, 2022). "Vδ2 T cells require the presence of BTN3A1 on tumor cells to detect intracellular IPP accumulation." (PMID 36002184, 2022). "BTN3A1 overexpression enhanced the malignancy of tumor cells." (PMID 36418890, 2022). "BTN3A1 in tumor samples was lower than in counterpart normal tissues in 31 of 38 (81.6%) BRCAs." (PMID 34293829, 2021). "The difference might be related to much more efficient BTN3A1 clustering on tumor cells than on normal cells, but potential adverse effects will need to be closely monitored in the ongoing trial." (PMID 32699351, 2020).